SLC38A2 (solute carrier family 38 member 2)
Diseases named in the same sentence as SLC38A2 in open-access papers (continued):
Sharing a sentence is not in itself a finding about the gene and the disease.
colorectal cancer (6 papers, 2021 to 2025). A primary or metastatic malignant neoplasm that affects the colon or rectum. "Here, we report that the majority of the KRAS mutant colorectal cancer (CRC) cells upregulate selected AATs (SLC7A5/LAT1, SLC38A2/SNAT2, and SLC1A5/ASCT2), which correlates with enhanced uptake of AAs such as glutamine and leucine." (PMID 34003553, 2021). "In the present study, using MRI, we determined the correlation between glutamine uptake and the distribution of glutamine transporters, namely ASCT2 and SLC38A2 (SNAT2), glutaminase (GLS), and CSC markers, such as CD44 and CD166, in a mouse xenograft model of HT29 human colorectal cancer cells." (PMID 35365739, 2022). "We also identified other SLC amino acid transporters, such as SLC38A2 and SLC1A5, with the potential to mediate serine transport but they did not seem essential for this process in colorectal cancer cells." (PMID 38066114, 2023). "Regarding SLC38A2, this may suggest that it is a plasma membrane-localized amino acid transporter capable of serine transport; however, as SLC38A2 silencing in HCT116 cells did not decrease serine uptake, it may not be a major endogenous mediator of serine transport in colorectal cancer cells." (PMID 38066114, 2023).
triple-negative breast carcinoma (6 papers, 2018 to 2025). An invasive breast carcinoma which is negative for expression of estrogen receptor (ER), progesterone receptor (PR), and human epidermal growth factor receptor 2 (HER2). "Upregulation of SLC38A2 has been observed in triple-negative breast cancer and hormone-resistant breast cancer, and it is associated with resistance to oxidative stress and the development of drug resistance, ultimately leading to poor clinical outcomes." (PMID 41040664, 2025). "Other glutamine transporters such as SNAT1 (SLC38A1) and SNAT2 (SLC38A2) have also been shown to play a role in glutamine uptake in triple-negative breast cancer, and in osteosarcoma and cervical cancer cells." (PMID 29940911, 2018). "SLC38A2 (also known as SNAT2) is a glutamine transporter that, when overexpressed, induces resistance to oxidative stress in triple-negative breast cancer cell lines." (PMID 41226631, 2025).
Obesity (5 papers, 2015 to 2024). Accumulation of substantial excess body fat. "Parental high-fat diet increased offspring obesity and type 2 diabetes mellitus risks through the regulation of SLC28A2 (solute carrier family 38 member 2) expression, which indicated that lncRNA-SLC28A2 may be associated with chicken lipid synthesis." (PMID 34249911, 2021).
fetal growth restriction (4 papers, 2011 to 2023). A fetus that does not grow beyond the 10th percentile of conventionally accepted weight for gestational age. "While TNF can stimulate sodium-coupled neutral amino acid transporter 2 (Slc38a2/SNAT2) in placental tissue, which supplies the fetus with amino acids required for growth, it has also been established that a low placental Slc38a2/SNAT2 expression level results in fetal growth restriction." (PMID 36142765, 2022).
prostate carcinoma (4 papers, 2019 to 2024). A carcinoma that arises from epithelial cells of the prostate gland. "This uptake of sarcosine was first believed to be mainly PAT- (SLC36) mediated, but it appears that SNAT2 (SLC38A2) also plays an important role in sarcosine uptake in prostate cancer cells, at least in vitro." (PMID 38399253, 2024).
diabetes (3 papers, 2021 to 2025). "SLC38A2 is upregulated in β cells in diabetes as a response to the translational repression associated with ER stress." (PMID 41465472, 2025).
Alzheimer disease (2 papers, 2024 to 2026). A progressive, neurodegenerative disease characterized by loss of function and death of nerve cells in several areas of the brain leading to loss of cognitive function such as memory and language. "Among these genes were Klhl2, which has been shown to induce neuronal apoptosis, and Slc38a2, known to be associated with Alzheimer’s disease and modulated by nutritional stress, like amino acid deprivation." (PMID 39456952, 2024).
breast tumors (2 papers, 2024 to 2025). "Apart from SLC7A8, all the following amino acid transporters, SLC7A5, SLC3A2, SLC7A11 and SLC38A2, were significantly expressed in breast tumours with high SLC1A5 expression (P < 0.01)." (PMID 39843491, 2025).
heart failure (2 papers, 2021 to 2025). Inability of the heart to pump blood at an adequate rate to meet tissue metabolic requirements. "To get the robust gene signature in heart failure, we overlapped genes from LASSO and SVM-RFE and got six gene signatures, including PALLD, DDX39A, CD164, CLDND1, SLC38A2, and CALU." (PMID 34926621, 2021).
leukaemia (2 papers, 2023 to 2025). "To test this further by genetic complementation, we first determined whether SLC38A2 is required for the proliferation of MA9 leukaemia cells." (PMID 40425534, 2025).
melanoma (2 papers, 2022). A malignant, usually aggressive tumor composed of atypical, neoplastic melanocytes. "To emphasize the importance of glutamine transporters in melanoma, we investigated the gene expression of glutamine transporters SLC38A1/SNAT1, SLC38A2/SNAT2, SLC1A5/ASCT2, and SLC7A5/LAT1, which showed expression in RNA sequencing analysis in several melanoma cell lines." (PMID 35565278, 2022). "As MeAIB does not just selectively inhibit SNAT1/SLC38A1, but also SNAT2/SLC38A2 and SNAT4/SLC38A4, we further analyzed specific SNAT1 effects using an siPool for selective downregulation of SNAT1 mRNA in melanoma cells." (PMID 35565278, 2022).
colorectal tumor (1 paper, 2021). "Eventually, our in vitro findings are reinforced by the analysis of the TCGA gene expression datasets, showing that selected AATs (SLC1A5/ASCT2, SLC7A5/LAT1, and SLC38A2/SNAT2) are significantly upregulated in primary colorectal tumor tissues, compared with normal tissues." (PMID 34003553, 2021).
lung carcinoma (1 paper, 2023). "Notably, higher SLC38A2 expression is associated with poor survival in lung cancer patients whose tumors exhibited SMARCA4 deletion, but not in patients whose tumors did not harbor SMARCA4 alterations." (PMID 37210563, 2023).
mastitis (1 paper, 2024). Inflammation of breast tissue during lactation or postpartum due to an obstructed duct or infection. "Similarly, the expression of genes related to lactation and other mammary traits (SLC38A2, SLC35B1), fertility (SLC38A2, MT1E), susceptibility to paratuberculosis, mastitis and trypanosomiasis (IL6), and feed intake/efficiency (MT1E, SLC38A2) was upregulated in Mirandesa cattle." (PMID 39333243, 2024).
pancreatic ductal adenocarcinoma (1 paper, 2022). An infiltrating adenocarcinoma that arises from the epithelial cells of the pancreas. "Pancreatic ductal adenocarcinoma cells upregulate SLC38A2 to increase alanine uptake and fuel proliferation." (PMID 36213239, 2022).
preeclampsia (1 paper, 2022). Preeclampsia is a hypertensive disorder of pregnancy that is characterized by new-onset hypertension with proteinuria presenting after 20 weeks of gestation, and depending on mild or severe forms may initially present with severe headache, visual disturbances, and hyperreflexia. "We assessed gene and protein expressions of SLC38A1, SLC38A2, and SLC38A4 in IUGR alone or preeclampsia + IUGR placental samples collected from early preterm (<34 weeks) gestation and compared these to gestationally matched uncomplicated preterm controls." (PMID 36613847, 2022). "We next assessed gene and protein expressions of SLC38A1, SLC38A2, and SLC38A4 in IUGR alone or in preeclampsia + IUGR placental samples collected from late preterm (34–36 weeks) gestation and compared these to gestationally matched controls." (PMID 36613847, 2022).
systemic hypertension (1 paper, 2022). "Interestingly, SLC38A2, a calcium transporter that shows a significant increase in both mRNA and protein and splicing factor, and the suppressor of white-apricot homolog (SFSWAP), which is increased in protein expression analysis, are implicated in systemic hypertension." (PMID 36176278, 2022).
Urea (1 paper, 2022). "SLC38A2 was the only one glycine transporter detected in No Wash sample, whereas SLC6A9 and SLC36A1 were specifically found in Urea Wash sample." (PMID 35085786, 2022).
tumor (45 papers, 2014 to 2025). "SLC38A2 shows widespread changes in expression patterns within tumor tissues, making it an effective diagnostic and prognostic biomarker." (PMID 41040664, 2025). "Solute carrier family 38 member A2 (SLC38A2) is a glutamine transporter closely linked to the high accumulation of glutamine within tumor cells." (PMID 41040664, 2025). "And by the using of bioinformatics methods, we comprehensively analyzed these data to elucidate the biological functions of SLC38A2 across various cancer types and its associations with tumor immunity and clinical prognosis." (PMID 41040664, 2025). "Loss of FLCN in DCs selectively impairs cDC1 function in vivo in a TFEB-dependent manner and phenocopies SLC38A2 deficiency by eliminating the anti-tumour therapeutic effect of glutamine supplementation." (PMID 37407815, 2023). "Collectively, these results show that SLC38A2 deficiency in tumour cells markedly impairs tumour growth in a cDC1-dependent manner." (PMID 37407815, 2023). "Subsequently, the association between SLC38A2 expression and the status of tumor-infiltrating immune cells, based on the levels of immune marker genes in GC, was investigated." (PMID 36918802, 2023). "Further, we generated SLC38A2-deficient B16-OVA (Cas9+) tumour cells and performed stable isotope tracing assays of glutamine and other known substrates of SLC38A236,37." (PMID 37407815, 2023). "By comprehensively incorporating gene expression and clinical data from the TCGA tumor database, GTEx database, Human Protein Atlas, and GEO database, we analyzed the expression profile, mutations, and established prognostic models for SLC38A2 across various cancers." (PMID 41040664, 2025). "Notably, there is a certain level of enrichment of SLC38A2 in tumor-associated stromal cells, such as epithelial cells, endothelial cells, and fibroblasts." (PMID 41040664, 2025). "Furthermore, research has revealed that SLC38A1 and SLC38A2 show increased expression levels in tumor cells, promoting tumorigenesis and closely associating with tumor cell proliferation and migration." (PMID 38358002, 2024). "To test this hypothesis, we generated SLC38A2-deficient tumour cells using single guide RNA (sgRNA) targeting Slc38a2 (sgSlc38a2)—or non-targeting control (sgNTC)—to delete SLC38A2 in Cas9-expressing MC38 cells." (PMID 37407815, 2023). "To test whether SLC38A2 acts in a tumour-intrinsic manner or requires the immune system for its in vivo effects, we examined growth of SLC38A2-deficient MC38 tumours in Batf3–/– or Rag1–/– mice." (PMID 37407815, 2023). "Additionally, we discovered that SLC38A2 expression is associated with tumor immune subtypes." (PMID 41040664, 2025). "It has been shown that tumor cells and type 1 conventional dendritic cells (cDC1) compete for Gln uptake via the transporter protein SLC38A2 to modulate anti-tumor immunity." (PMID 40598593, 2025). "Given its crucial role in the competitive uptake of glutamine by tumor cells, SLC38A2 is likely an effective molecular marker for reflecting tumor malignancy, immune suppression status, and clinical outcomes." (PMID 41040664, 2025). "Considering the elevated expression of PHGDH, SLC1A5 and SLC38A2 in CRC and their association with tumour proliferation, metastasis and patient prognosis, we selected these genes for validation in real‐world patient cohorts." (PMID 40660426, 2025). "Critically, PHGDH, PSAT1, PSPH, SLC1A4, SLC1A5 and SLC38A2 show robust co‐expression patterns in both TCGA tumour samples and CCLE cancer cell lines, suggesting coregulated functionality." (PMID 40660426, 2025). "In the present work, we find that micropeptide hSPAR acts as an intrinsic regulator of glutamine metabolism by repressing the glutamine transporter SLC38A2 and demonstrate that glutamine deprivation is the key to mediating the anti-tumor effect of hSPAR." (PMID 39875724, 2025).
tumor (continued). "This study further confirms the role of the key transporter SLC38A2 in glutamine metabolism across various cancers, encompassing clinical aspects, the tumor microenvironment, immunity, and drug sensitivity." (PMID 41040664, 2025). "cDC1s and tumor cells compete for glutamine in the tumor microenvironment via the transporter protein SLC38A2 to modulate anti-tumor immunity, and glutamine is the key amino acid promoting the antigen-presenting function of cDC1s77." (PMID 39781535, 2025). "We found that SLC38A2 is positively correlated with stromal scores and negatively correlated with immune scores across various cancers, supporting the notion that SLC38A2 is a key player in tumor stroma remodeling and immune suppression." (PMID 41040664, 2025). "To further elucidate the role of SLC38A2 in tumor immunity, we conducted a comprehensive analysis of its correlation with the pan-cancer immune landscape." (PMID 41040664, 2025). "This indicates that SLC38A2 becomes irreversibly enriched in the “unfavorable” cell subgroups during the late stages of tumor progression, ultimately leading to immune cell exhaustion due to glutamine deprivation." (PMID 41040664, 2025). "To further elucidate the association between SLC38A2, the TME, and tumor-associated cells, we utilized single-cell sequencing data analysis to evaluate the expression patterns of SLC38A2 across 12 types of cancer." (PMID 41040664, 2025). "This reflects the critical role of SLC38A2-mediated glutamine competitive inhibition in blocking antigen presentation, leading to tumor immune suppression." (PMID 41040664, 2025). "In CRC tissues, PHGDH, SLC1A5 and SLC38A2 were mainly expressed in tumour cells and the GCs of mature TLSs." (PMID 40660426, 2025). "In liver metastases, PHGDH and SLC38A2 were expressed in tumour cells, surrounding hepatocytes and bile duct cells." (PMID 40660426, 2025). "Targeting SLC38A2 presents a viable therapeutic strategy by inhibiting glutamine competition and relieving immune suppression in the tumor microenvironment." (PMID 41040664, 2025). "Binds Annexin A2/p65 to activate NF-κB, upregulating SLC38A2/SLC7A5 to enhance glutamine uptake in tumor cells." (PMID 41409273, 2025). "Tumor cells and cDC1s compete for glutamine uptake via the transporter SLC38A2 to tune anti-tumor immunity." (PMID 40688069, 2025). "This evidence suggests that SLC38A2 regulates glutamine uptake in tumor and immune cells and plays a central role in adaptive T cell immunity." (PMID 41040664, 2025). "Consistent with cohort 1, the expression patterns of PHGDH, SLC1A5 and SLC38A2 in normal and tumour tissues from cohort 2 were identical for all three markers." (PMID 40660426, 2025). "Our objective is to employ bioinformatics methods to conduct a comprehensive and in-depth analysis of SLC38A2 across various cancers, aiming to elucidate its role and prognostic value in tumor biology." (PMID 41040664, 2025). "Although many studies have confirmed that blocking glutamine metabolism pathways significantly inhibits tumor progression, research and targeted drugs specifically for SLC38A2 remain limited." (PMID 41040664, 2025). "Mechanistically, tumor cells and cDC1s compete for glutamine uptake via the transporter SLC38A2, which modulates anti-tumor immunity." (PMID 39050845, 2024). "Similar to HIF-1α, HIF-2α can induce the expression of SLC38A2, SNAT2, SLC1A5 variant, GLS1, and SLC7A5, which can facilitate the rapid growth of tumor cells." (PMID 38172980, 2024). "Another study explored the expression patterns of SLC38A2 in both tumor and immune cells, revealing significantly higher expression levels in tumor cells and dendritic cells compared to CD8 + T cells and other immune cells." (PMID 38459595, 2024). "DCs and tumor cells both express SLC38A2 to facilitate glutamine uptake, modulating anti-tumor immunity." (PMID 38218942, 2024).
tumor (continued). "Colony formation, Cell Counting Kit-8, wound healing, Transwell and tumor formation assays were performed to assess the biological function of SLC38A2." (PMID 36918802, 2023). "Of the shared cDC1 and cDC2 markers, the glutamine importer encoded by Slc38a2 especially caught our attention, because very recently, SLC38A2 and glutamine signaling specifically in cDC1s was shown to dictate anti-tumor immunity in vivo." (PMID 38077407, 2023). "Tumour cells and cDC1s rely on the glutamine transporter SLC38A2 for glutamine uptake and downstream biological effects." (PMID 37407815, 2023). "Glutamine uptake is indispensable for tumor cell growth and metastasis; in LUAD, SLC38A2 plays a key role in driving glutamine endocytosis and causing glutamine addiction." (PMID 37091977, 2023). "Further, SLC38A2 expression in tumour cells restricts the access of cDC1s to glutamine, consistent with high glutamine uptake by tumour cells in the TME7." (PMID 37407815, 2023). "To establish the functional importance of SLC38A2 in tumour cells in mediating tumour–immune interactions, we challenged wild-type mice with sgNTC- or sgSlc38a2-transduced MC38 or B16-OVA cells, and found slower tumour growth upon SLC38A2 deletion." (PMID 37407815, 2023). "The results demonstrated that SLC38A2 potentially promoted tumor development in GC, including tumor growth, metastasis and immune infiltration." (PMID 36918802, 2023). "The results demonstrated that SLC38A2 knockdown significantly reduced tumor induction and formation." (PMID 36918802, 2023). "Further, tumour cells expressed higher SLC38A2 protein levels than intratumoral cDC1s and CD8+ T cells." (PMID 37407815, 2023). "This likely occurred during tumor development, potentially through the selection of cells naturally expressing high levels of SLC38A2 or adaptive metabolic reprogramming that remain to be investigated." (PMID 37210563, 2023). "Similar results were obtained upon genetic deletion of Slc38a2 in T cells (Cd4creSlc38a2fl/fl mice) in the MC38 tumour model." (PMID 37407815, 2023). "Mechanistically, tumour cells and cDC1s compete for glutamine uptake via the transporter SLC38A2 to tune anti-tumour immunity." (PMID 37407815, 2023). "MC38 tumour growth was increased in Xcr1cre/+Slc38a2fl/fl mice, indicating the selective requirement of SLC38A2 in cDC1s for tumour control." (PMID 37407815, 2023). "The results demonstrated that SLC38A2 enhanced GC cell proliferation and metastasis in vitro, as well as GC tumor formation in vivo." (PMID 36918802, 2023). "The results demonstrated that SLC38A2 was significantly correlated with tumor purity in GC (ρ=-0.132; P = 1.01 × 10− 2)." (PMID 36918802, 2023). "Conversely, exosomes from sh-LINC01614 transduced CAFs inhibited tumor growth in the xenografts, accompanied by a reduced expression of Ki67, SLC38A2, and SLC7A5." (PMID 36209111, 2022). "We demonstrate that the SLC38A2 anti-tumour effect is partially mediated by oxidative stress and that high SLC38A2 protein expression in a large clinical cohort correlates with poor BCSS in patients and particularly those with TNBC." (PMID 33028955, 2021). "High SLC38A2 expression was related to younger patient age, high tumour grade, moderate/poor Nottingham Prognostic Index and TNBC (all p < 0.01), but not with lymph node status." (PMID 33028955, 2021). "While the exact transporters involved in serine uptake within tumours remain incompletely defined, members of the solute carrier (SLC) superfamily, such as SLC1A4 (ASCT1), SLC1A5 (ASCT2), SLC7A10, SLC38A2, SLC38A4 and SLC38A5, have been implicated." (PMID 40660426, 2025). "This dual effect reflects the complex role of SLC38A2 in tumor immune modulation." (PMID 41040664, 2025). "In the TME, tumor cells and cDC1s compete for glutamine uptake through the SLC38A2 transporter." (PMID 41041303, 2025).